KIF4A (kinesin family member 4A)
Diseases named in the same sentence as KIF4A in open-access papers (continued):
Sharing a sentence is not in itself a finding about the gene and the disease.
tumor (continued). "KIF4A is implicated in tamoxifen resistance (regulated by ANCCA/MLL), serves as a hub gene within EMT-related ceRNA networks, and maintains CSC properties (its inhibition diminishes tumour sphere formation capacity." (PMID 41361459, 2025). "Considering the different expression patterns of KIF4A in tumors, interfering with KIF4A expression may be a novel strategy for tumor treatment." (PMID 38937742, 2024). "Thus, targeting KIF4A is a promising therapeutic approach to cancer therapy by inducing apoptosis of tumor cells." (PMID 37039264, 2023). "Previous studies indicated that enhanced KIF4A expression predicted poor prognosis and promoted tumor growth in OS and down-regulation of KIF4A could suppress the colony formation, invasion and migration and cell cycle of OS cells." (PMID 36849972, 2023). "Specifically, KIF4A was found to be expressed in tumor cells, T cells, monocytes, and fibroblasts." (PMID 37370891, 2023). "Additionally, we also revealed the potential relationship between KIF4A and ERCC6L, that is, there was a direct interaction between KIF4A and ERCC6L, and both are closely associated with mitosis and contribute to tumor growth and metastasis." (PMID 37667329, 2023). "In addition, Houet al. found that Kif4A is upregulated in CRC tumor tissue and cells, and regulates cell proliferation by inhibiting p21 transcription." (PMID 35882623, 2022). "With the progression of tumor, the expression of KIF4A was upregulated (p < 0.05)." (PMID 35126794, 2022). "In addition, we also analyzed the prediction value of KIF4A in status (tumor or normal), and the ROC curve results showed that KIF4A had a terrific predictive performance (AUC:0.978)." (PMID 35126794, 2022). "In addition, upregulated KIF4A is associated with age, survival status, grade, FIGO stage, histological type, tumour invasion, and TCGA molecular subtypes (p < 0.05)." (PMID 35126794, 2022). "The findings demonstrated that KIF4A knockdown suppressed tumor growth of ESCC in vivo." (PMID 34775374, 2021). "We observed that KIF4A is necessary for tumor growth in vivo." (PMID 34326322, 2021). "Intriguingly, whether in HCC or ICC, many genes (such as ADRA1A and KIF4A) displayed some opposite features of AS events in tumor and normal tissues." (PMID 34760694, 2021). "At tumor onset, mice were treated with doxycycline to induce KIF4A knockdown or control." (PMID 34326322, 2021). "Data confirmed that KIF4A mRNA levels were significantly elevated in tumour tissues (72/78, 92.3%)." (PMID 29396392, 2018). "We found that KIF4A might be a potential diagnostic marker for distinguishing normal and tumor tissues, and KIF4A mRNA expression in tumor tissues were elevated in all cohorts, with AUC reaching 0.787, 0.998 and 0.97 respectively." (PMID 28646197, 2017). "More importantly, we observe that, expression of CCL2 in both two types’ cells is significantly inhibited upon Kif4A silencing via siRNA, suggesting a potential modulatory-supportive role of this motor protein in establishment of tumor microenvironment in OSCC." (PMID 28533507, 2017). "Furthermore, high KIF4A expression is associated with advanced FIGO stage, high tumour grade, specific TCGA molecular subtypes, and the presence of various tumour-infiltrating immune cells, indicating its profound role in regulating the EC immune microenvironment." (PMID 41361459, 2025). "Consequently, targeting KIF4A may not only inhibit tumour growth directly but also help reverse immunosuppression, transforming “cold” tumours into “hot” ones." (PMID 41361459, 2025).
tumor (continued). "Similarly, KIF4A, ZWINT, and UBE2C are involved in cell cycle regulation, cell proliferation, and mitosis, with frequent dysregulation observed in cancers and a clear association with tumor progression and poor clinical outcomes." (PMID 39684488, 2024). "Nonetheless, the role of ERCC6L and KIF4A in tumor progression remains unclear." (PMID 37667329, 2023). "KIF4A is closely related to the formation of a spindle during mitosis and the completion of cytoplasmic division and intracellular transport of chemicals, because DNA damage can lead to abnormal cell proliferation and differentiation, which ultimately promotes tumour formation." (PMID 35126794, 2022). "Moreover, E-cadherin level is downregulated, and vimentin expression is up after KIF4A knockdown, suggesting that KIF4A could promote tumor invasion and metastasis through EMT in vitro." (PMID 34775374, 2021). "Additionally, KIF4A knockdown significantly restricted tumor growth in vivo." (PMID 34775374, 2021). "Mechanistically, KIF4A enhances the expression of the chemokine CXCL5, which recruits myeloid-derived suppressor cells (MDSCs) to the tumour microenvironment, thereby inhibiting antitumor immunity, facilitating immune evasion, and promoting tumour growth." (PMID 41361459, 2025). "The resultant increase in KIF4A drives LSCC cell proliferation and migration while inhibiting apoptosis; conversely, KIF4A knockdown mitigates the pro-tumour effects of ERCC6L overexpression." (PMID 41361459, 2025). "Mechanistically, KIF4A upregulates CCL2, which binds to the CCR2 receptor on macrophages, facilitating their recruitment and polarization towards the pro-tumour M2 phenotype." (PMID 41361459, 2025). "miR-195 inhibits KIF4A expression by directly targeting its 3’UTR, leading to a reduction in tumour volume by over 40% in vivo models while significantly promoting apoptosis." (PMID 41361459, 2025). "InccRCC, a 4-gene model comprising KIF4A, UBE2C, OTX1, and PPP2R2C showed great potential to distinguish tumour tissues from normal ones." (PMID 41361459, 2025). "KIF4A protein expression was detected by IHC in both NSCLC and SCLC tumours, and KIF4A transcript levels were identified as overexpressed in LUAD compared to non-malignant tissues." (PMID 40002279, 2025). "Our findings revealed that the expression levels of the hub genes—UBE2T, KIF4A, CDCA3, and CDCA5—were correlated with various clinical aspects of HCC, including cancer stages, nodal metastasis status, tumor grade, and histological subtypes." (PMID 38890649, 2024). "Six of them (KIF4A, ASPM, KIF20A, KIF14, TPX2, KIF18B) warrant particular attention as they show increased expression by more than 10-fold in tumor samples compared to normal tissues." (PMID 37835564, 2023). "Six of them (KIF4A, ASPM, KIF20A, KIF14, TPX2, KIF18B) are overexpressed by more than 10-fold in tumor samples and four of them (KIF11, AURKB, TPX2 and KIFC1) are essential for cell survival." (PMID 37835564, 2023). "After analyzing the single-cell dataset, it was discovered that IQGAP3, KIF4A, and WASIR1 were expressed in immune cells, indicating their potential involvement in regulating the tumor immune microenvironment in PCa." (PMID 37370891, 2023). "To further determine the expression of KIF4A in BC, we analyzed GSE7904, finding that KIF4A expression was distinctly upregulated in BC specimens compared with non-tumor specimens." (PMID 35646102, 2022). "Consistently, NUF2, KIF4A, KIF18B, DLGAP5, and NEK2 were highly overexpressed, whereas LRRK2 was significantly downregulated in the tumor tissues of all datasets." (PMID 36499051, 2022). "These candidates included five upregulated genes—NUF2, KIF4A, KIF18B, NEK2, and DLGAP5—and one downregulated gene—LRRK2—in the tumor tissues of TCGA databases." (PMID 36499051, 2022).
tumor (continued). "Kinesin family member 4A (KIF4A) is a highly related gene; it promoted progression in various tumor tissues by regulating chromosome segregation machinery in mediating spindle organization and cytokinesis." (PMID 34034774, 2021). "All 6 KIFs selected by LASSO regression were seen overexpressed in tumor samples comparing to normal samples (KIF10, KIF15, KIF18B, KIF4A: P < 0.0001; KIF18A: P = 0.0003; KIF20A: P = 0.0022), which in accordance with bioinformatics results." (PMID 32322170, 2020). "a–c mRNA expression of FOXM1 (a), KIF4A (b), and CENPF and KIF20A (c), in human HCC and non-tumor tissues based on data from TCGA." (PMID 31072351, 2019). "SHCBP1, KIF4A, and ECT2 have been reported to mediate tumor initiation and progression of human HCC." (PMID 31392101, 2019). "Subsequently, we further evaluated the endogenous KIF4A expression in 492 (86.6%) of 568 CRC samples and 493 (86.8%) of 568 non-tumor tissues in the TMAs using immunohistochemistry (IHC)." (PMID 29706624, 2018). "We further confirmed that both KIF4A mRNA and protein expressions were overexpressed in human HCC tumour tissues as well as cancer cell lines." (PMID 29396392, 2018). "Current evidence suggests that inhibiting KIF4A can reduce MDSC recruitment and enhance cytotoxic T cell infiltration, providing a rationale for combining it with immune checkpoint inhibitors to overcome barriers in tumour immunotherapy resistance." (PMID 41361459, 2025). "Additionally, exosomes from normal human chondrocytes deliver miR-195 to OS cells, targeting the KIF4A 3’UTR to inhibit its expression, resulting in a about 40% reduction in tumour volume in vivo and a marked decrease in OS growth." (PMID 41361459, 2025). "Our analysis supported three kinesin genes (KIF4A, KIF20A, and KIF11) that may play a key role in tumor initiation and progression by regulating cell proliferation and division." (PMID 41462522, 2025). "KIF4A was observed significantly higher mRNA and protein expression in HCC tissues, and the mRNA expression of KIF4A correlated markedly with individual cancer stages and tumor grades." (PMID 38890649, 2024). "Finally, KIF4A, KIF13A, KIF13B, and KIF26A were identified from the HPA database, and all these KIFs differentially expressed between normal and tumor samples." (PMID 36837615, 2023). "We demonstrated that KIF4A protein was strongly expressed in human UBC tumor tissue and UBC cell lines compared with that in noncancerous tissue and normal urothelial cells, respectively." (PMID 37039264, 2023). "Meanwhile, it should also be noted that the expression of KIF4A was not statistically correlated with the following clinical characteristics: BMI and tumor residual." (PMID 35126794, 2022). "The increased expression of KIF4A is remarkably related to multiple factors, including age, FIGO stage, histological type, grade, tumor invasion, and OS status (p < 0.05)." (PMID 35126794, 2022). "Among the top 100 genes that have similar expression patterns of KIFC1 in the tumors of the TCGA cohort, the KIFC1 expression was significantly and positively correlated with KIF2C, NCAPH, KIF4A, TPX2, and CDCA5 expression in all of the tumor types in the TCGA database." (PMID 35327439, 2022). "Indeed, the present study showed that CCNA2, CEP55, KIF11, KIF4A, and ZWINT were the top five genes that were significantly and positively correlated with CDK1 in all tumor types from the TCGA database." (PMID 35681641, 2022). "Among pathways and gene signatures differentially expressed between our tumor and adjacent normal samples (FDR q ≤ 1e-4), the CIN70 gene signature was enriched with genes positively correlated with Signature 17 activities (e.g., TPX2, NEK2, and KIF4A)." (PMID 33257699, 2020). "The results show that BIRC5, CENPA, KIF4A, DTYMK, PRC1, and TRIP13 have low beta values in tumor." (PMID 32391055, 2020).
tumor (continued). "High expression of FOXM1 was positively correlated with poor histological grade and advanced tumor–node–metastasis (TNM) stage in HCC; while elevated KIF4A level was positively correlated with vascular invasion, as well as poor histological grade and late TNM stage." (PMID 31072351, 2019). "Our results showed that knocking down KIF4A expression suppresses FOXM1 mediated HCC cell proliferation and tumor growth, suggesting that FOXM1–KIF4A axis may be a potential therapeutic target for HCC treatment." (PMID 31072351, 2019). "A paired Wilcoxon test of 454 cases, pairing the tumor tissue and its adjacent non-cancerous tissue, revealed that KIF4A protein expression was dramatically upregulated in cancerous tissue compared to adjacent non-cancerous tissue (P < 0.001)." (PMID 29706624, 2018). "The expression of CCNB2, KIF4A, and TPX2 were upregulated in the advanced tumor stages." (PMID 30254986, 2018). "Among them, CCNB2, KIF4A, and TPX2 were further upregulated in advanced tumor stage." (PMID 30254986, 2018). "Gene Silencing Therapy: Silencing KIF4A expression through siRNA, shRNA, or CRISPR-Cas9 technology (in vitro and in vivo mouse xenograft models) has been demonstrated to effectively inhibit tumour growth, reverse chemotherapy resistance, and enhance the immune microenvironment." (PMID 41361459, 2025). "Thus, we further hypothesized whether KIF4A and TYMS might be considered as the tumor marker in the diagnosis of early OC." (PMID 31987036, 2020). "Moreover, our data demonstrated that elevated KIF4A expression was significantly correlated with clinicopathological parameters such as a deeper depth of invasion, advanced TNM stage, increased tumor diameter, increased lymph node metastasis and distant metastasis, and poorer OS and DFS." (PMID 29706624, 2018). "Evidence is emerging that over expression of KIF4A and KIF18A may play roles in tumor progression." (PMID 24327603, 2013). "Further analysis at the protein level confirmed that KIF4A and IQGAP3 were upregulated in tumor tissues instead of normal tissues from the HPA database." (PMID 37370891, 2023). "Seven pairs of tumor and adjacent non-tumorous tissues were selected to verify the expressions of the ZWINT, RRM2, NDC80, KIF4A, CEP55, CENPU, and CENPF genes." (PMID 35028418, 2022). "To further validate the relationship between KIF4A expression status and HCC, we detected the mRNA level of tumour tissues compared with paired non-cancerous tissues using qPCR." (PMID 29396392, 2018). "The expression level of KIF4A was significantly correlated with the grade of ESCC differentiation (P = 0.0227) and lymph node metastasis (P = 0.0016), but not with patient sex, age, and tumor size (P > 0.05)." (PMID 36046597, 2022).
cancer (63 papers, 2013 to 2025). A tumor composed of atypical neoplastic, often pleomorphic cells that invade other tissues. "Considering that our clinical data indicated that high KIF4A expression is associated with cancer metastasis, we performed Transwell assays to investigate the effect of KIF4A on CRC cell migration and invasion." (PMID 29706624, 2018). "From a translational perspective, utilizing KIF4A expression profiles to develop diagnostic and prognostic models has demonstrated good clinical applicability, and its characteristic pan-cancer upregulation is particularly advantageous for formulating broad-spectrum targeting strategies." (PMID 41361459, 2025). "KIF4A has been reported to be associated with a variety of cancer lesions." (PMID 34055488, 2021). "Our findings revealed that high expression of KIF4A could serve as a diagnostic and prognostic marker in OS cancers." (PMID 34055488, 2021). "High KIF4A expression is significantly associated with poor prognosis in a variety of cancers." (PMID 33718157, 2021). "KIF4A overexpression can serve as a diagnostic and prognostic marker in various cancers." (PMID 34055488, 2021). "KIF4A is unusual for a kinesin, in that it has also been found to be required for DNA damage responses and decreased KIF4A activity is associated with cancer." (PMID 33836947, 2021). "Our bioinformatics analysis results showed that overexpression of KIF4A played a role in mitosis and could become a potential new diagnostic and prognostic marker for various cancers." (PMID 34055488, 2021). "In conclusion, KIF4A could be used as a biomarker and prognostic indicator for pan-cancer diagnostic." (PMID 34055488, 2021). "KIF4A (Kinesin Family Member 4A) is a microtubule-based motor protein involved in maintaining chromosome integrity during cell mitosis; it was implicated as an potential biomarker in types of cancers." (PMID 31119182, 2019). "Our result also indicates increased KIF4A mRNA expression significantly associated with short survival in other nine cancer type, which suggested KIF4A may play essential oncogenic role of in various malignant cancer progression." (PMID 28646197, 2017). "Besides, study based on TCGA cohorts also reveals high KIF4A mRNA expression are significantly associated with shorter overall survival in multiple cancer types." (PMID 28646197, 2017). "We aimed to explore whether KIF4A could be used as a biomarker of pan-cancer diagnostic." (PMID 34055488, 2021). "KIF4A could serve as a pan-cancer diagnostic and prognostic marker." (PMID 34055488, 2021). "Beyond its classical mitotic functions, emerging evidence positions KIF4A as a central regulator of tumorigenesis, therapy resistance, metabolic reprogramming, and immune modulation across diverse cancer types." (PMID 41361459, 2025). "Although KIF4A exhibits cancer-type-specific mechanisms, these individual observations converge into several shared molecular patterns across malignancies." (PMID 41361459, 2025). "Furthermore, KIF4A exhibits differential expression in tissues affected by COVID-19 and those with digestive system cancers, highlighting its involvement in cell division pathways and offering fresh insights into the mechanisms underlying the interaction between infection and cancer." (PMID 41361459, 2025). "KIF4A also correlates with the mRNA stemness index (mRNAsi), suggesting a role in supporting EC cancer stem cell characteristics." (PMID 41361459, 2025). "As our understanding of its functional mechanisms deepens and innovative treatment modalities continue to emerge, targeting KIF4A holds the potential to offer new hope to many patients, particularly those with cancer facing treatment challenges." (PMID 41361459, 2025). "A significant hurdle for KIF4A’s clinical translation is its dual biological roles—functioning as an “oncogene” in cancer yet serving as an “essential gene” for normal cellular processes such as mitosis and nervous system function." (PMID 41361459, 2025).